RFX6 (regulatory factor X6)
Diseases named in the same sentence as RFX6 in open-access papers (continued):
Sharing a sentence is not in itself a finding about the gene and the disease.
prostate carcinoma (13 papers, 2012 to 2026). A carcinoma that arises from epithelial cells of the prostate gland. "We also examined rs339331 T > C, an oncoprotective variant in an RFX6 enhancer, where upregulation of RFX6 is associated with prostate cancer progression and metastasis." (PMID 41495882, 2026). "Intriguingly, a genome‐wide association study identified GPRC6A/RFX6 as a susceptible locus for prostate cancer in a Japanese population, first revealing a link between RFX6 and tumourigenesis." (PMID 38093528, 2023). "The risk-associated allele at rs339331 increases HOXB13 binding in a transcriptional enhancer, resulting in the allele-specific upregulation of RFX6, which enhances prostate cancer cell proliferation, migration, and invasion." (PMID 33919522, 2021). "In prostate cancer, on the one hand, clinical data showed that the upregulated expression of RFX6 was associated with the risk of tumor progression, metastasis, and biochemical recurrence." (PMID 34840985, 2021). "HOXB13 acts as a transcription factor and, together with the androgen receptor (AR) and FOXA1, regulates expression of the RFX6 gene which encodes a driver of prostate cancer progression." (PMID 32546843, 2020). "In the clinical setting, RFX6 upregulation in human prostate cancer correlates with tumor progression, metastasis, and risk of biochemical relapse." (PMID 31013831, 2019). "This gene is nearby to RFX6, which harbors an intronic variant (rs339331) that has been reported in a GWAS of prostate cancer in Japanese men." (PMID 23555315, 2013). "The related genes, C2orf43, FOXP4, GPRC6A and RFX6, are warranted for further efforts to determine the functional variations and finally to clarify the genetic mechanism of susceptibility to prostate cancer." (PMID 22662242, 2012). "Our results provide further support for association of the C2orf43, FOXP4, GPRC6A and RFX6 genes with prostate cancer in Eastern Asian populations." (PMID 22662242, 2012). "Interestingly, HOXB13 is preferentially recruited to the risk allele of a prostate cancer risk associated SNP, rs339331, located in an enhancer element upstream of RFX6, thereby enhancing RFX6 expression and promoting more aggressive disease." (PMID 32546843, 2020). "This suggests the RFX6 gene variation may be the susceptibility loci underlying the observed association signal of the GPRC6A/RFX6 loci with prostate cancer in the original GWAS." (PMID 22662242, 2012). "Notably, around the loci of the GPRC6A and RFX6 genes, the SNPs significantly associated with prostate cancer narrowed to the region of the RFX6 gene, compared to a wide distribution of significantly associated SNPs across the whole region of these two genes in the original GWAS." (PMID 22662242, 2012). "In subsequent studies, suppression of RFX6 profoundly diminished the development of prostate cancer and HCC, highlighting its pro‐tumoural functions." (PMID 38093528, 2023). "Together, this study presented the first example of a regulatory risk SNP being responsible for prostate cancer pathogenesis through cooperation with the prostate-lineage-specific transcription factor, HOXB13, to regulate a novel oncogene, RFX6." (PMID 31013831, 2019). "For example, the last four exons of UBE2Q1 and last five exons of RFX6 contributed to increased expression levels in prostate cancer tissues." (PMID 26979803, 2016). "We successfully replicated the association of rs13385191 (located in the C2orf43 gene, P = 8.60×10−5), rs12653946 (P = 1.33×10−6), rs1983891 (FOXP4, P = 6.22×10−5), and rs339331 (GPRC6A/RFX6, P = 1.42×10−5) with prostate cancer." (PMID 22662242, 2012). "According to the previous reports, RFX6 can be used as a marker of prostate cancer." (PMID 32462000, 2020). "The prostate cancer risk-associated T allele at rs339331 increases chromatin binding of HOXB13 to an active transcriptional enhancer, conferring allele-specific upregulation of the target gene, RFX6." (PMID 31013831, 2019).
type 2 diabetes (11 papers, 2014 to 2026). "RFX6 is also mutated in autosomal recessive syndrome of neonatal diabetes and shows reduced expression in beta cells in early type 2 diabetes." (PMID 38353726, 2024). "Recent studies have also shown RFX6 variants to be linked with type 2 diabetes." (PMID 39080045, 2024). "Furthermore, genome-wide association studies link RFX6 variants to type 2 diabetes and analysis of multiomics data from individuals with type 2 diabetes reveals genetic regions enriched with RFX-binding motifs." (PMID 39080045, 2024). "All these observations refute the diagnosis of MRS in this family; however, according to the literature, individuals with RFX6 heterozygous variants may be more susceptible to develop type 2 diabetes at a younger age." (PMID 38162681, 2023). "It remains possible that heterozygous carriers of RFX6 5′ mutations may have increased risk of early-onset type 2 diabetes." (PMID 26264437, 2015). "Moreover, genome-wide association studies have associated variants of RFX6 with type 2 diabetes." (PMID 38743124, 2024). "Single-cell transcriptomics and epigenetic profiling of human islets have identified RFX6 as an important transcriptional factor in the early stages of type 2 diabetes pathophysiology." (PMID 40088285, 2025). "In adult primary islets, RFX6 was shown to be a hub transcription factor that was downregulated in islets from donors with early type 2 diabetes, correlated with reduced GSIS." (PMID 38743124, 2024). "Knockdown of RFX6 in clonal beta cells also leads to dysregulation of cilia genes, which resembles the transcriptional changes observed in early type 2 diabetes, and dysregulation of Rfx genes and ciliogenesis has been observed in metabolically stressed cells." (PMID 38353726, 2024). "A recent study also demonstrated that RFX6 knockdown in primary human islets reduced GSIS to the level seen in islets from donors with type 2 diabetes, through transcriptionally dysregulated vesicle trafficking, exocytosis and ion transport pathways." (PMID 38743124, 2024). "However, our findings are in line with the beta cell-specific Rfx6 knockout in adult mice and confirm the reported reduction of insulin secretion in islets from donors with type 2 diabetes as a result of reduced RFX6 levels." (PMID 38743124, 2024). "Therefore, Rfx6 might be an interesting target should “β cell-identity drugs” be developed in the future as a novel therapeutic strategy in type 2 diabetes." (PMID 25497096, 2014). "Of the 132 type 2 diabetes Knowledge Portal effector genes, we identified 18 (14%) as candidate effector genes for at least one phenotype, including ABCC8, KCNJ11, NKX2–2, G6PC2, PAM, HNF4A, SLC30A8, RFX6, PCSK1, and GLIS3." (PMID 37333221, 2023). "However, a similar strategy will not help to distinguish late onset RFX6-MODY from type 2 diabetes." (PMID 29026101, 2017).
Mitchell-Riley syndrome (9 papers, 2015 to 2024). "The phenotypic spectrum observed in our patients with PDX1-NDM overlaps with features seen in Mitchell-Riley syndrome caused by recessive RFX6 variants (OMIM:615710)." (PMID 39542526, 2024). "The degree of pancreatic and gallbladder involvement in Mitchell-Riley Syndrome appears to be associated with the specific RFX6 gene mutation, with some patients retaining residual pancreatic activity, thereby suggesting a genotype–phenotype correlation." (PMID 36422736, 2023). "RFX6 (OMIM#612659) mutations are supposed to cause NDM by the formation of a flawed RFX6 protein in Mitchell-Riley syndrome." (PMID 34584998, 2021). "The genetic studies done for Mitchell-Riley syndrome (RFX6 gene locus) confirmed presence of a homozygous mutation in the RFX6 gene (c.1153C>T p.Arg385*), a previously unreported homozygous mutation in exon 11 of the RFX6 gene." (PMID 26761945, 2016). "In conclusion, we have reported a confirmed case of Mitchell-Riley syndrome with a previously unreported homozygous mutation in exon 11 of the RFX6 gene." (PMID 26761945, 2016). "Homozygosity mapping has identified chromosomal regions linked to Mitchell-Riley syndrome, in which the regulatory factor X 6 (RFX6) gene was identified." (PMID 26770845, 2015). "The association of the particular phenotype of Martinez-Frias syndrome with a mutation on the RFX6 gene and neonatal diabetes has been called Mitchell-Riley syndrome, and it was suggested that both syndromes represent a symptom continuum or an RFX6 malformation complex." (PMID 26770845, 2015). "All the seven probands previously reported with Mitchell-Riley syndrome presented RFX6 mutations." (PMID 26770845, 2015). "A novel RFX6 homozygous missense mutation was identified in an infant with Mitchell-Riley syndrome." (PMID 26770845, 2015). "Herein, a novel RFX6 mutation is reported in an infant with Mitchell-Riley syndrome." (PMID 26770845, 2015). "Using this new approach, we model Mitchell-Riley syndrome with RFX6 knockout hPSCs illustrating unexpected morphogenesis defects in the differentiation towards islet cells." (PMID 39003281, 2024). "After other gene testing was negative, the clinical diagnosis of Mitchell-Riley syndrome was ultimately considered and further genetic analysis revealed a novel missense homozygous variant in RFX6: c.983A>T (p.asp328Val)." (PMID 31275908, 2019). "This is the first reported case of a classical Mitchell-Riley syndrome in the Arab peninsula along with additional features and novel mutations in the RFX6 gene." (PMID 26761945, 2016).
intestinal atresia (3 papers, 2015 to 2023). A congenital malformation characterized by the absence of a normal opening in a part of the intestine. "In patients with intestinal atresia, gallbladder agenesis, and neonatal diabetes, RFX6 mutation should be considered." (PMID 35813646, 2022). "Biallelic mutations in RFX6 (regulatory factor X, 6) cause neonatal diabetes mellitus in association with intestinal atresias, and hepatobiliary abnormalities." (PMID 26264437, 2015).
jejunal atresia (3 papers, 2015 to 2024). "The so-called Mitchell–Riley syndrome (OMIM #615710), another rare syndromic form of NDM, is a condition caused by homozygous mutation in the RFX6 gene and is characterized by pancreatic hypoplasia leading to permanent NDM, duodenal and jejunal atresia, and gall bladder agenesis." (PMID 39408828, 2024). "The data presented support the idea that biallelic mutations in RFX6 should be considered in any infant presenting with duodenal or jejunal atresia with or without intestinal malrotation, especially in the context of possible autosomal recessive inheritance." (PMID 26264437, 2015). "Homozygous mutations in the transcription factor (TF) RFX6 are the cause of the MRS associating neonatal diabetes congenital digestive system defects, including biliary atresia, pancreatic hypoplasia, duodenal and/or jejunal atresia, intestinal malrotation, gallbladder aplasia, and cholestasis." (PMID 34715892, 2021).
melanoma (3 papers, 2020 to 2022). A malignant, usually aggressive tumor composed of atypical, neoplastic melanocytes. "Another study suggested RFX6, as a prognostic biomarker for melanoma." (PMID 36045400, 2022). "In addition, RFX6 has also been reported to be differentially expressed in melanoma, liver cancer, GC, and other cancer tissues, but the further molecular mechanism remains to be explored." (PMID 34840985, 2021). "We constructed a 6-gene signature (IQCE, RFX6, GPAA1, BAHCC1, CLEC2B, and AGAP2) as a novel prognostic marker for predicting the survival of melanoma patients." (PMID 32462000, 2020). "In addition, immunohistochemistry analysis demonstrated that IQCE, RFX6, GPAA1, BAHCC1, CLEC2B, and AGAP2 were highly expressed in melanoma tissues compared with normal tissue." (PMID 32462000, 2020). "In order to verify whether IQCE, RFX6, GPAA1, BAHCC1, CLEC2B, and AGAP2 were highly expressed in melanoma tissues as predicted, we experimentally confirmed this by qRT-PCR and immunohistochemical staining using melanoma tissues extracted from 10 patients." (PMID 32462000, 2020).
neonatal diabetes mellitus (3 papers, 2015 to 2024). Neonatal diabetes mellitus presents as hyperglycemia, failure to thrive and, in some cases, dehydration and ketoacidosis which may be severe with coma, in a child within the first months of life. "Biallelic mutations in RFX6 are associated with permanent neonatal diabetes mellitus (PNDM), with affected individuals exhibiting smaller size pancreas compared with healthy control individuals." (PMID 39080045, 2024).
duodenal atresia (2 papers, 2016 to 2022). Duodenal atresia is an embryopathy of the cranial intestine that leads to a complete absence of the duodenal lumen. "Caused by biallelic mutations of the gene encoding the transcription factor RFX6, the rare Mitchell–Riley syndrome (MRS) comprises neonatal diabetes, pancreatic hypoplasia, gallbladder agenesis or hypoplasia, duodenal atresia, and severe chronic diarrhea." (PMID 35813646, 2022). "We report a case with neonatal diabetes, pancreatic hypoplasia gall bladder agenesis, duodenal atresia, haemochromatosis, hypospadias and intrauterine growth restriction with some additional features along with a different mutation in the RFX6 gene which has not been reported before." (PMID 26761945, 2016). "Here, we report a case with neonatal diabetes, pancreatic hypoplasia, gall bladder agenesis, duodenal atresia, haemochromatosis, hypospadias, and intrauterine growth retardation (IUGR) with some additional features along with a different mutation in the RFX6 gene which has not been reported before." (PMID 26761945, 2016).
hepatocellular carcinoma (2 papers, 2021 to 2023). A malignant tumor that arises from hepatocytes. "Elevated regulatory factor X6 (RFX6) expression serves as an independent prognostic factor associated with poor outcomes in hepatocellular carcinoma (HCC)." (PMID 38093528, 2023). "Since miRNA-542-3p suppresses RFX6 expression in hepatocellular carcinoma cells, we wonder if such regulation affects the tumorigenesis of liver cells." (PMID 34988028, 2021). "In the meantime, a series of biological experiments in vivo and in vitro were conducted to analyze the biological significance of RFX6 in hepatocellular carcinoma." (PMID 34988028, 2021). "The DNA-binding protein RFX6 was overexpressed in hepatocellular carcinoma, and its expression level was correlated with the prognosis and immune cell infiltration in liver hepatocellular carcinoma." (PMID 34988028, 2021). "The relative protein expression of RFX6 in hepatocellular carcinoma tissues was higher than that in adjacent normal tissues." (PMID 34988028, 2021). "Furthermore, we discovered that miRNA-542-3p, the expression of which was decreased in hepatocellular carcinoma, was directly involved in the negative regulation of the expression of RFX6." (PMID 34988028, 2021). "Our discovery of the functional link between miRNA-542-3p, RFX6, and DTX2 plays critical roles in hepatocellular carcinoma and provides potential therapeutic targets for hepatocellular carcinoma treatment." (PMID 34988028, 2021).
Hyperglycemia (2 papers, 2014 to 2023). An increased concentration of glucose in the blood. "Interestingly, fasting hyperglycemia has been reported in a patient bearing a heterozygote mutation in the RFX6 gene and SNP susceptibility to T2D, supporting a role for RFX6 in β cell function in humans." (PMID 25497096, 2014). "The resulting Rfx6ΔBeta mice are glucose intolerant in contrast to the phenotype of the Rfx6 null mice, which die shortly after birth with severe and sustained hyperglycemia (>600 mg/dl)." (PMID 25497096, 2014).
liver cancer (2 papers, 2021). An epithelial or non-epithelial malignant neoplasm that arises from the liver. "We demonstrated that knockdown of RFX6 in liver cancer cells significantly suppressed the proliferation, migration, and invasion of cancer cells." (PMID 34988028, 2021). "However, the mechanism of the abnormal expression and the biological effects of RFX6 in liver cancer remains unknown." (PMID 34988028, 2021). "To understand the specific expression mechanism of RFX6 in liver cancer, we performed bioinformatic prediction, CHIP-qPCR assay, co-IP, and dual-luciferase assay to assess the regulating mechanism of RFX6." (PMID 34988028, 2021).
type 1 diabetes (2 papers, 2017 to 2020). "Given that RFX6 is also expressed in the pancreas, we also examined the association of anti-RFX6 antibodies with APS1-associated type 1 diabetes." (PMID 32410729, 2020). "We observed that 6/7 APS1-associated type 1 diabetes samples had positive signal for anti-RFX6 antibodies by RLBA." (PMID 32410729, 2020).
Adrenal insufficiency (1 paper, 2020). Insufficient production of steroid hormones (primarily cortisol) by the adrenal glands. "Among these were the associations of KHDC3L with ovarian insufficiency, RFX6 with diarrheal-type intestinal dysfunction, CYP11A1 (also known as cholesterol side chain cleavage enzyme) with adrenal insufficiency (AI), and SOX10 with vitiligo." (PMID 32410729, 2020).
anemia (1 paper, 2022). A reduction in the number of red blood cells, the amount of hemoglobin, and/or the volume of packed red blood cells. "The limitations of this study include a lack of functional analyses of the RFX6 compound heterozygous mutations and the unexplained mechanism related to severe anemia." (PMID 35813646, 2022).
autoimmune disease (1 paper, 2020). A disorder resulting from loss of function or tissue destruction of an organ or multiple organs, arising from humoral or cellular immune responses of the individual to their own tissue constituents. "Future studies will help to determine whether testing for anti-RFX6 antibodies possesses clinical utility for prediction or diagnosis of specific APS1 autoimmune disease manifestations as well as for non-APS1 autoimmune disease." (PMID 32410729, 2020).
Autoimmunity (1 paper, 2020). The occurrence of an immune reaction against the organism's own cells or tissues. "Using detailed clinical phenotyping, we find novel associations between autoantibodies and organ-restricted autoimmunity, including a link between anti-KHDC3L autoantibodies and premature ovarian insufficiency, and between anti-RFX6 autoantibodies and diarrheal-type intestinal dysfunction." (PMID 32410729, 2020).
Glucose intolerance (1 paper, 2014). Glucose intolerance (GI) can be defined as dysglycemia that comprises both prediabetes and diabetes. "Rfx6 loss in adult β cells leads to glucose intolerance, impaired β cell glucose sensing, and defective insulin secretion." (PMID 25497096, 2014). "Conditional inactivation of Rfx6 in adult β cells led to insulin secretion deficiency and glucose intolerance, although insulin was still produced." (PMID 25497096, 2014).
hemochromatosis (1 paper, 2012). A disorder of iron metabolism characterized by a triad of HEMOSIDEROSIS; LIVER CIRRHOSIS; and DIABETES MELLITUS. "The coded DNA-binding protein RFX6 plays an important role in the pathology of neonatal hemochromatosis." (PMID 22662242, 2012).
Hypoglycemia (1 paper, 2013). A decreased concentration of glucose in the blood. "Severe hypoglycemia appears to be the primary cause of death in Pdx-1-Creearly;VhlhLoxP/LoxP (and Rfx6-Cre;VhlhLoxP/LoxP and Ngn3-Cre;VhlhLoxP/LoxP) pups." (PMID 23977255, 2013). "Rfx6-Cre;VhlhLoxP/LoxP pups exhibited severe postnatal hypoglycemia with associated lethality." (PMID 23977255, 2013). "Summarily, our results indicate that secretion of glucagon is impaired in islets lacking Vhlh and suggest a likely mechanism for the hypoglycemia in Pdx-1-Creearly;VhlhLoxP/LoxP, Ngn3-Cre;VhlhLoxP/LoxP and Rfx6;VhlhLoxP/LoxP mice." (PMID 23977255, 2013).
Immunodeficiency (1 paper, 2021). Failure of the immune system to protect the body adequately from infection, due to the absence or insufficiency of some component process or substance. "Mutations in RFX5 in humans lead to severe immunodeficiency, but, interestingly, mutations in the similar protein RFX6 cause malformations of the gut." (PMID 34020589, 2021).